HMGA2 (high mobility group AT-hook 2)
Diseases named in the same sentence as HMGA2 in open-access papers (continued):
Sharing a sentence is not in itself a finding about the gene and the disease.
tumor (continued). "In agreement with our identification of HMGA2 as an important driver of CHOL carcinogenesis, overexpression of HMGA2 was reported in various cancers, and it was implicated in tumor metastasis, poor prognoses, and therapy failures in various cancer." (PMID 34831096, 2021). "HMGA2 overexpression due to chromosomal rearrangements was strongly linked to tumor malignancy, including LPS." (PMID 34206586, 2021). "HMGA2 is aberrantly expressed in several types of cancer, with high levels of HMGA2 associated with a highly malignant phenotype, as it is related to increased tumor proliferation, invasiveness, and stemness and reduced survival." (PMID 33731207, 2021). "In GC, overexpression of miR-503 impeded cell proliferation, invasion and colony formation in vitro and tumor growth in vivo by suppressing target gene HMGA2 (encoding High-mobility group AT-hook 2) and WNT/β-catenin signaling pathway." (PMID 33762949, 2021). "HMGA2 is associated with tumour grade, growth, metastasis, poor prognosis and epithelial mesenchymal transition of PC." (PMID 34552050, 2021). "Several studies demonstrated that the biological functions of HMGA2 are associated with various behaviors of tumor cells, such as proliferation, invasion, and metastasis; thus, HMGA2 is an attractive target for cancer treatment." (PMID 32842685, 2020). "According to driver alterations, MED12 was mutated in 4 tumours (MED12mut) while HMGA2 upregulation was detected in tumour L23." (PMID 32251338, 2020). "Individual let-7 family members have also been implicated in a variety of tumor pathogenic mechanisms involving HMGA2." (PMID 32365712, 2020). "As the underlying mechanism of the oncogenesis, the effects of HMGA2 on cellular proliferation, invasion, the epithelial–mesenchymal transition, and apoptosis inhibition have been reported in various tumor cells." (PMID 32489328, 2020). "High mobility group AT-hook 2 (HMGA2) has been associated with increased cell proliferation and cell cycle dysregulation, leading to the ontogeny of varied tumor types and their metastatic potentials, a frequently used index of disease prognosis." (PMID 32365712, 2020). "One such regulatory element is the let-7 microRNA family of tumor suppressors which have conserved complementary binding sites encoded in the 3’-UTR of the HMGA2 gene." (PMID 32365712, 2020). "The enrichment of epithelial–mesenchymal transition (EMT) and angiogenesis was coincident with the causal role of HMGA2 in tumor metastasis." (PMID 31581665, 2019). "Detailed histological analyses did not uncover any differences in the histological features of mice with Hmga2-deficient or Hmga2-wildtype tumours." (PMID 30228296, 2018). "These authors found, using immunohistochemical analysis, that the elevated expression of HMGA2 in tumor cells was associated with tumor aggressiveness." (PMID 29495500, 2018). "Abundance of fragments encoding tumour-associated genes Hmga2, Fos, Myc, Nras and Jun in DNA libraries." (PMID 28222152, 2017). "TTF-1/HMGA2 axis was associated with tumor differentiation and mediated the aggressiveness of the tumor and prognosis." (PMID 29079814, 2017). "Tumours with elevated HMGA2 expression are associated with a poor prognosis and an elevated incidence of metastasis." (PMID 28533522, 2017). "So, HMGA2 was a tumor stage independent prognostic factor associated with high incidence of tumor recurrence in blastemal WT patients." (PMID 29383160, 2017). "HMGA2 was associated with tumour differentiation, TNM stage, metastasis and recurrence and positively correlated with VM." (PMID 28533522, 2017). "No clear consensus binding sequence has been found in the published ChIP experiments of Hmga2 association to chromatin in a human tumor cell line except for A/T-rich stretches." (PMID 27036552, 2016). "HMGA2 overexpression in various human neoplasias is associated with highly malignant phenotypes, such as chemoresistance, metastasis, and poor survival." (PMID 26893968, 2016).
tumor (continued). "Conversely, several studies have reported that the association of HMGA2 overexpression with the transformation and metastatic progression of neoplastic cells suggests its causal role in carcinogenesis and tumor progression." (PMID 26893968, 2016). "Other tumor suppressors of the let-7 family increase the expression of HMGA2 (high mobility group AT-hook 2), which is associated with tumor invasion and is an independent prognostic factor in GC." (PMID 27322246, 2016). "The result showed that, 39/60 (65 %) TSCC had much higher expression of HMGA2, which was significantly associated with a more aggressive tumor phenotype (P < 0.001)." (PMID 26818837, 2016). "The tumor was also investigated for expression of HMGA2, HMGA1, and MED12 as well as for possible mutations in exon 2 of MED12." (PMID 25621995, 2015). "Inactivation of one allele of Hmga2 in the intestinal epithelium significantly reduced disease penetrance and tumor burden in Vil-Lin28bMed/Hmga2+/IEC-KO mice." (PMID 26244988, 2015). "Several oncogenes are known to be targets of the let-7 miRNA family, including Ras, c-Myc, and Hmga2, and the repression of let-7 has been linked to several types of tumor, such as lung, breast, and ovarian cancer." (PMID 24475120, 2014). "In oral squamous cell carcinomas, strong staining of HMGA2 and loss of E-cadherin expression were observed at the invasive front of tumor." (PMID 25548562, 2014). "Overexpression of HMGA2 is associated with aggressive tumor growth, early metastasis, and poor prognosis." (PMID 24743780, 2014). "HMGA2 overexpression has been associated with tumor growth, differentiation, metastasis, unfavorable outcome and resistance to treatment." (PMID 23251297, 2013). "Increasing LIN28A was associated with down-regulation of tumor suppressing microRNAs let-7b and let-7g and up-regulation of the chromatin modifying protein HMGA2." (PMID 23846349, 2013). "A2780 and CH1 approximated C5 tumours most closely, as both expressed low levels of Let-7 alleles, and high levels of HMGA2 and LIN28B." (PMID 21533284, 2011). "The truncated transcripts of HMGA2 with a partial or complete loss of let-7 complementary sites can explain the increased expression of HMGA2 in tumours with slight reduction or regular level of let-7 expression." (PMID 19156147, 2009). "By comparing malignant and non‐malignant epithelial cells in PSC, malignant cells showed high expression of marker genes associated with epithelial–mesenchymal transition (EMT) and tumour metabolism regulation related genes, such as HMGA2, FN1, PDE10A, and PCAT1." (PMID 41469334, 2026). "Also, a High HMGA2 levels were noticed to be significantly associated with advanced tumor stage, higher tumor grade, and muscle invasion (p < 0.05)." (PMID 40853523, 2025). "Similarly, the downregulation of let-7 miRNA family members enhances the expression of HMGA2, a chromatin remodeling factor associated with increased tumor aggressiveness." (PMID 40429954, 2025). "Otherwise, amplification of HMGA2 has been reported in adipocytic tumors associated with a favorable prognosis, as it may contribute to tumor differentiation." (PMID 40141463, 2025). "High mobility group protein 2 (HMGA2) is an essential component of the enhanceosome that regulates gene transcription during organ development, and its re-expression in adult tissues is often linked to tumor formation and progression." (PMID 40518465, 2025). "Furthermore, HMGA2 overexpression is associated with poor prognosis, high tumor grade, and lymph node metastasis." (PMID 38845972, 2024). "It has been reported that HMGA2 exhibits a strong association with tumor metastasis and growth." (PMID 37998349, 2023). "In addition to its role as an oncoprotein associated with aberrant expression in several tumor types, HMGA2 promotes a cancer stem cell phenotype, chemoresistance, and is involved in adipogenesis at the clonal expansion step from preadipocytes to adipocytes." (PMID 36119484, 2022).
tumor (continued). "However, the prolonged treatment appeared insufficient, as shown by the development of tumor relapse due to the loss of the let-7-binding site in the 3′UTRs of some oncogenes such as HMGA2." (PMID 35563051, 2022). "Silencing HMGA2 can cause tumor cell apoptosis by arresting cell growth in the G2/M phase." (PMID 35400282, 2022). "Importantly, similar to NUF2, higher HMGA2 expression was associated with higher tumor grades, advanced TNM stages, metastases, and poor OS and DFS." (PMID 35813477, 2022). "Our findings show that HMGA2 deficiency was sufficient to suppress the xenograft tumor growth in vivo, which support our hypothesis that HMGA2-induced renal carcinogenesis occurs at least in part through the regulation of tumor associated EMT genes." (PMID 35439951, 2022). "HMGA2 also plays a critical role in embryonic stem cell development and its dysregulation in adult somatic cells can lead to carcinogenesis; mutation of the HMGA2-encoding gene is observed widely in diverse types of tumor." (PMID 34072941, 2021). "However, we compared expression profiles between tumor grades and found that SNX15, ATP2A1, PDCD10, BET1, and HMGA2 expressions were significantly (all p < 0.05) associated with tumor stages." (PMID 34831096, 2021). "Moreover, repressing HMGA2 expression reversed the positive effect of circFAM73A on xenograft tumor formation, while exogenous expression of HMGA2 attenuated the effects caused by circFAM73A disruption." (PMID 33731207, 2021). "Moreover, miR-490-3p/HMGA2 axis was validated to be underlying the tumor-suppressive role of hsa_circ_0006948 in ESCC." (PMID 33957921, 2021). "Since HMGA2 positively correlates with distant metastasis and poor survival rates HMGA2 could be available as a potential diagnostic and prognostic tumor marker." (PMID 34072941, 2021). "Additionally, we showed using both gain-of-function and loss-of-function assays that HMGA2 was required for tumor formation in vivo." (PMID 32489328, 2020). "Overall survival, primary tumour burden, presence of disseminated tumour cells in the peritoneal cavity or circulating tumour cells in the blood, and presence and number of metastases were not significantly different between mice with Hmga2-wildtype or Hmga2-deficient tumours." (PMID 30228296, 2018). "In addition, the expression of the HMGA2 is associated with tumour stage and clinical outcomes in ovarian carcinoma." (PMID 29391048, 2018). "TTF-1/HMGA2 asix is associated with tumor differentiation and aggressiveness." (PMID 29079814, 2017). "We found that upon LLC development, enhanced levels of fragments encoding tumour-specific genes Hmga2, Fos, Myc and Jun were detected in the blood of tumour-bearing mice, and after DNase I treatment levels of all fragments except for Fos-specific ones were reduced." (PMID 28222152, 2017). "Moreover, most cancer cell lines of the basal B subtype expressed high levels of HMGA2 and suffered a loss of E-cadherin, suggesting that in such tumours, invasiveness promoted by the loss of E-cadherin is a likely event." (PMID 25492890, 2015). "This study suggests that let-7a/HMGA2 may play an important role in tumor metastasis and may be a novel diagnostic marker and potential therapeutic target in NPC." (PMID 25884389, 2015). "Overexpression of HMGA2 is associated with tumour growth and metastatic progression." (PMID 25492890, 2015). "HMGA2 may be involved in tumor cell invasion due to its association with epithelial-mesenchymal transition that facilitates tumor cell invasion." (PMID 25548562, 2014). "Furthermore, animal models have shown that HMGA2 silencing is associated with reduction in tumor growth and increased apoptosis of tumor cells." (PMID 22235203, 2012). "Members of the let-7 family play a major role in cell differentiation and are considered to act as tumor suppressors by silencing numerous genes that encode oncogenic proteins including HMGA2, insulin-like growth factor 2-binding protein 1 (IGF2BP1), RAS and c-MYC." (PMID 21853155, 2011).
tumor (continued). "Consequently, the fusion is predicted to cause a loss of function of HMGA2, which may contribute to the pathogenesis of the tumor by impairing its normal gene regulatory functions." (PMID 41568362, 2025). "In contrast, the ‘tumor cells 2’ cluster was characterized by genes associated with protein synthesis (Cmss1, Rpph1, Rps12, Lars2, Ncl2), tumorigenesis (Mt-Rnr2, Hmga2, Mab1b) and cell–cell communication (Gphn, Camk1d, Il31ra, Cmss1, Rpph1), which may be indicative of an inflammatory phenotype." (PMID 39769061, 2024). "Thus, it would be of particular interest to examine whether knockdown or inhibition of MFAP4, NPTX1, and/or HMGA2 suppresses tumor development of BAP1-deficient MMe cells." (PMID 37479714, 2023). "Positive HMGA2 expression was significantly associated with a higher pT status, a higher pN status, a higher overall pathological stage, poorer cell differentiation, positive perineural invasion, and greater tumor depth (P = 0.036, < 0.001, < 0.003, < 0.001, < 0.001, and < 0.001, respectively)." (PMID 26138061, 2015). "For instance, we utilised bulk RNA sequencing data from publicly available databases to validate the elevated mRNA expression of HMGA2 in tumour tissues." (PMID 41469334, 2026). "CAs and HMGA2-canalicular-like PAs exhibited similar histology and immunostaining but differed significantly in tumor site and transcriptomic profiles." (PMID 42052924, 2026). "In the present study, CAs and the HMGA2-canalicular-like PAs mostly shared similar histology and immunostaining, while the clinical presentations regarding tumor site and transcriptomic profiles were different." (PMID 42052924, 2026). "In parallel, loss of let-7 unleashes HMGA2 and RAS/MYC signaling, a traditional tumor-suppressive axis described across epithelial tumors and reported in gynecologic contexts." (PMID 41226475, 2025). "HMGA2 staining was found in 5963 (37.5%) of the 15,915 interpretable tumor samples, including 1914 (12%) with weak, 1838 (11.5%) with moderate, and 2211 (13.9%) with strong positivity." (PMID 40518465, 2025). "HMGA2-expressing thyrocytes were predominantly localized in areas of the tumor where the follicular structure was altered, whereas thyroglobulin staining was detected in the colloid of follicles that had retained their structure." (PMID 40004107, 2025). "HMGA2 expression was significantly higher in tumor cells located farther from acinar cells, whereas GATA6 expression was elevated in tumor cells in close proximity to acinar cell nests, although effect sizes were limited." (PMID 41006303, 2025). "In vivo, studies demonstrated that HMGA2-mediated regulation of macrophage polarization through the CXCL12/CXCR4 axis significantly promotes tumor metastasis." (PMID 40351420, 2025). "ESTIMATE algorithm analysis further revealed significantly elevated stromal scores (P<0.01), immune scores (P<0.01), and ESTIMATE scores (P<0.001) alongside reduced tumor purity (P<0.001) in HMGA2-low tumors (all vs HMGA2-high)." (PMID 40703517, 2025). "HMGA2 is widely recognized as a novel oncogene that significantly influences tumor initiation, progression, and prognosis." (PMID 40351420, 2025). "At the same time, HMGA2 is highly expressed in a variety of tumor tissues, and it promotes tumor growth, epithelial–mesenchymal transition, metastasis, and invasion." (PMID 40821116, 2025). "Of the 15,915 tumor samples, 37.5% showed HMGA2 positivity: 12% weak, 11.5% moderate, and 13.9% strong." (PMID 40518465, 2025). "Functional experiments also indicated that knocking down HMGA2 significantly inhibited the proliferation, migration, and invasion of EC tumor cells." (PMID 40703517, 2025).
tumor (continued). "Consistent with our findings in human PDAC, the basal marker HMGA2 was expressed at lower levels in tumor cells located within lobules compared to those in stromal regions, while GAL4 expression was higher in lobular areas." (PMID 41006303, 2025). "Although the tumor cells uniformly expressed HMGA2 protein in all cases, cytokeratin 7, S100 protein, and SOX10 displayed either diffuse positivity or highlighted the luminal and abluminal cell populations, respectively." (PMID 40033554, 2025). "HMGA2 expression demonstrated strong correlations with advanced tumor staging, aggressive molecular subtypes, and high-grade histopathology." (PMID 40703517, 2025). "Transcription factors (TFs) associated with tumor metastasis and progression, such as SOX9, HMGA2, TP63, NFIL3, and IRF6, exhibited high transcriptional activity in the ITGA2hi‐PTC subcluster." (PMID 40985182, 2025). "Western blot analysis revealed that HMGA2 protein expression was significantly upregulated in OSCC tumor tissues compared to normal tissues." (PMID 40900300, 2025). "Although there were only 4.6% of cancers with moderate or strong HMGA2 positivity, these tumors almost exclusively showed unfavorable tumor parameters and poor outcomes." (PMID 40518465, 2025). "Our study demonstrates that TPA and mezerein significantly induce transformed foci formation and proliferation in Bhas42 cells through the epigenetic regulation of Hmga2 and Ezh2, suggesting their role in tumour progression." (PMID 40182023, 2025). "Our preliminary data suggested HMGA2 contributed to the occurrence and development of EC through transcriptional regulation of tumor proliferation and immune microenvironment suppression." (PMID 40703517, 2025). "Due to the current limited use of molecular analysis of PA and CXPA, a high-quality, prospective cohort of HMGA2-altered neoplasms is difficult to collect." (PMID 40338436, 2025). "Next, we quantified IF for the basal tumor marker, HMGA2, and the classical marker, GAL4, and used the acinar marker, AMY, to confirm regions of lobular invasion." (PMID 41006303, 2025). "A total of 118 of 144 tumor categories showed HMGA2 expression in at least one case, and 92 tumor categories included at least one case with strong HMGA2 staining." (PMID 40518465, 2025). "The high prevalence of HMGA2 expression in many tumor types argues against a strong role of HMGA2 IHC for the distinction of tumor entities." (PMID 40518465, 2025). "The patients were classified according to tumor stage and EAU classification, and the association between each classification and plasma HMGA2 levels was investigated." (PMID 40204943, 2025). "Of note, the presence of high levels of HMGA2 RNA and protein in some tumor types has prompted the search for potential inhibitors and anti-HMGA2 therapies." (PMID 40518465, 2025). "This differential expression pattern was consistently replicated in our institutional cohort, molecular confirmation via RT-qPCR and western blotting of 30 matched tumor-normal pairs confirmed profound HMGA2 transcript and protein overexpression in EC tissues." (PMID 40703517, 2025). "That HMGA2 positivity was seen in 118 of 144 tumor entities including 92 tumor entities with at least one strongly positive case is suggestive for an important role of HMGA2 in many cancer entities." (PMID 40518465, 2025). "In HCC cells, miR-375 suppresses tumor progression by directly targeting HMGA2, thereby inhibiting cell proliferation, glycolysis, and tumor growth, while promoting apoptosis." (PMID 41158508, 2025). "Multiple studies have shown that the overexpression of HMGA2 can drive tumor development or promote the invasiveness of tumors." (PMID 40900300, 2025). "Let-7 showed direct targets oncogenes such as RAS, HIF-1α and HMGA2, thus inhibiting tumor growth and metastasis." (PMID 40429954, 2025).